PTGDR2 (prostaglandin D2 receptor 2)
Diseases named in the same sentence as PTGDR2 in open-access papers (continued):
Sharing a sentence is not in itself a finding about the gene and the disease.
tumor (21 papers, 2013 to 2024). "Among them, the UALCAN database showed that CXCL3 was related to the trait of histological types in ESCA and READ, GPR44 (PTGDR2) was associated with tumor grade in ESCA and NPBWR1 was related to patients’ age in ESCA and READ." (PMID 33552958, 2020). "This study further demonstrated the critical role of the PGD2/PTGDR2 signaling cascade response in tumor biology." (PMID 39777337, 2024). "The hub gene ADCY6, CXCL3, NPBWR1, TAS2R38, and PTGDR2 highly influence the clinical traits of age, histology types, neoplasm histologic grade, and overall survival in ESCA and READ, leading to their similarity in these clinical traits." (PMID 33552958, 2020). "Our research shows that PTGDR2 is associated with the tumors’ grades in ESCA and its expression is higher with tumor grades increasing." (PMID 33552958, 2020). "Calcitriol or its analogues downregulated the expression of 4 genes related to the Th1 response in tumour tissue (Ifng (only calcitriol), Socs1, Tbx21 and Fasl) and upregulated 5 genes related to the Th2 response (Ccl11, Ptgdr2, Il9, Asb2 and Il5)." (PMID 31595196, 2019). "However, PGD2/PTGDR2 signaling pathway’s anti-tumor and treatment resistance effects are mediated by different mechanisms that are not yet fully understood, as described in the following paragraph." (PMID 38704736, 2024). "In addition, to elucidate the effect of PTGDR2 on the stemness of GCSCs, Western blot analysis was performed, which revealed that PTGDR2 knockout reduced tumor inhibition by PGD2 and increased GCSCs stemness." (PMID 39777337, 2024). "Additionally, the ability to inhibit PGD2’s tumor-suppressing effect after PTGDR2 knockdown indicates that the presence of PGD2 ligands is essential for PGD2’s tumor-suppressing effects." (PMID 38704736, 2024). "Furthermore, PTGDR2 exerts anti-inflammatory and anti-tumor effects by inhibiting the classical NF-κB signaling pathway as well as KRAS, MAPK, ERK1/2, and Akt-mediated transcription factor signaling pathways." (PMID 38704736, 2024). "Furthermore, prostaglandin E2 (PGE2) and its related receptors, as well as the prostaglandin D2 (PGD2)/PGD2 receptor (PTGDR2), play irreplaceable roles in tumorigenesis and anti-tumor therapy." (PMID 38704736, 2024). "Thus, EMT modulation can promote the tumor-suppressive effect of the PGD2/PTGDR2 pathway." (PMID 38704736, 2024). "In some tumor patients, PGD2 or PTGDR2 expression levels correlated with the occurrence of distant metastases." (PMID 38704736, 2024). "The PGD2/PTGDR2 pathway inhibits the protein expression of the metalloproteinases, MMP-2 and MMP-9, key mediators for tumor invasion and metastasis." (PMID 38704736, 2024). "Similarly, in mouse tumor models and patients, PGD2/PTGDR2 exhibits anti-tumor effects and PGE2 pro-tumor activity." (PMID 38704736, 2024). "Most of the transcriptomic signatures (without subgroup analysis) still show acceptable tumor specificity with the exception of the signature containing PTGDS, CBR3, PTGIR, PTGFR, PTGDR2, and PTGER3 genes in HNSC tumor, which is similar to other tumors (BRCA, CESC, LUAD, SARC, and UCES)." (PMID 35453789, 2022). "PGD2 and PTGDR2 could regulate the TME and related anti-cancer signals to exert anti-tumor effects." (PMID 38704736, 2024).
cancer (12 papers, 2013 to 2025). A tumor composed of atypical neoplastic, often pleomorphic cells that invade other tissues. "Low expression of PGD2 and PTGDR2 is associated with poor prognosis in different types of cancer." (PMID 38704736, 2024). "Therefore, combined protein and bioinformatics analyses of gene expression datasets indicated an association between dysregulated expression of PGD2 or PTGDR2 and the prognosis of different cancer patients." (PMID 38704736, 2024). "Several experiments have demonstrated that PGD2 signaling through PTGDR2 not only directly inhibits cancer cell survival, proliferation, and migration but also reduces resistance toward conventional chemotherapeutic agents." (PMID 38704736, 2024). "In general, the PGD2/PTGDR2 pathway is considered to be a signaling cascade that inhibits cancer cell survival, proliferation, and migration." (PMID 38704736, 2024). "This study assessed whether PGD2/PTGDR2 signaling regulates the self-renewal ability of GCSCs by activating autophagy, and also evaluated the molecular mechanisms underlying the activation of autophagy, to indicate if this signaling cascade can be used as a target for the treatment of cancer." (PMID 39777337, 2024). "PTGDR2, a transmembrane protein, may have more potential as cancer targets." (PMID 31781593, 2019). "Knockdown of PTGDR2 and PGD2 expression in cancer stem cells (CSCs) resulted in enhanced expression of CSC markers and self-renewal ability." (PMID 31781593, 2019). "This review focuses on the current understanding of PGD2/PTGDR2 expression patterns and biological activity in cancer, proposing questions to guide the assessment of PGD2 and its receptors as potential targets for effective cancer therapies." (PMID 38704736, 2024). "In summary, it was elucidated that the PGD2/PTGDR2 signaling cascade affects GCSCs stemness by regulating autophagy, suggesting that the PGD2/PTGDR2 signaling pathway could serve as a novel target for cancer therapy." (PMID 39777337, 2024). "PTGDR, PTGDR2, PTGER1, PTGER3, and PTGFR genes have the median expression value of about 1 FPKM (Fragments Per Kilobase Million), while other genes are expressed in the range of 1–5 FPKM, regardless of cancer specificity." (PMID 35453789, 2022).
PTGDR2 also shares sentences with these, for which no sentence is quoted: Allergy (11 papers); allergic asthma (7); inflammation (7); atopic dermatitis (6); COVID-19 (5); pulmonary fibrosis (5); acute promyelocytic leukemia (4); eosinophilic esophagitis (4); inflammatory bowel disease (4); chronic rhinosinusitis (3); airway hyperresponsiveness (2); chronic obstructive pulmonary disease (2); colon cancer (2); colorectal cancer (2); dermatitis (2); diabetes (2); food allergy (2); hyperglycaemia (2); idiopathic pulmonary fibrosis (2); infection (2); polyposis (2); renal fibrosis (2); respiratory diseases (2); type 2 diabetes (2); airway allergies (1); Alzheimer disease (1); Arthritis (1); atopic asthma (1); autoimmune disease (1); bacterial meningitis (1).
A further 59 diseases each share a sentence with PTGDR2 in 1 paper.